MET (MET proto-oncogene, receptor tyrosine kinase)
Diseases named in the same sentence as MET in open-access papers (continued):
Sharing a sentence is not in itself a finding about the gene and the disease.
gastric cancer (continued). "It has been reported that c-MET was highly expressed in many types of human cancers, such as liver, ovarian, non-small cell lung, gastric cancers, and pancreatic cancer." (PMID 25193856, 2014). "The findings from present study indicated that higher MET gene amplification and expression in gastric cancer was an indicator of poor prognosis." (PMID 24416238, 2014). "The present systematic review and meta-analysis shows that MET overexpression and gene amplification was an indicator of poor prognosis in patients with gastric cancer." (PMID 24416238, 2014). "MET, the hepatocyte growth factor receptor, is a receptor tyrosine kinase overexpressed and activated in a subset of gastric cancer." (PMID 24416238, 2014). "Sample 23 represented a primary gastric cancer; only ∼20–30% of the tumor cells revealed clustered gene amplification (MET:CEP7 ratio 14.93) (sample 23a), while the remainder of tumor cells were low polysomic (sample 23b)." (PMID 24983965, 2014). "The incremental expression of c-MET has been identified in hepatocellular carcinoma, gastric carcinoma and colon carcinoma." (PMID 24393368, 2014). "For gastric carcinoma (GC), aberrant MET activation has been thought to be related to a gene dosage effect, and MET gene amplification (GA) or protein overexpression has been associated with aggressive tumor characteristics and/or worse clinical outcome." (PMID 25364819, 2014). "The highest Met protein level was found in the MET amplified gastric carcinoma derived cell line MKN45 (800 pg Met/μg total protein), and the lowest was found in the human breast adenocarcinoma derived cell line MCF7 (1 pg Met/μg total protein)." (PMID 25534569, 2014). "Given that gastric cancer cell lines with MET amplification have been found to have a high copy number for MET, we arranged all cases in the order of MET copy number and performed FISH analysis for the 15 cases with the highest copy numbers." (PMID 23327903, 2013). "Our aim was to investigate both the prevalence of MET amplification in gastric cancer as well as the potential of this genetic alteration to serve as a therapeutic target in gastric cancer." (PMID 23327903, 2013). "Elevated expressions of c-MET and its ligand, HGF, have been frequently found in gastric cancer, and are associated with a more aggressive disease." (PMID 24330856, 2013). "On the other hand, an increase in MET copy number was found in 10 to 20% of gastric cancer patients by Southern blot analysis or with a PCR-based assay." (PMID 23327903, 2013). "We first applied FISH and a real-time PCR–based method to examine MET copy number in gastric cancer cell lines whose MET amplification status was previously determined." (PMID 23327903, 2013). "In gastric cancer, the tumorigenic potential of some proto-oncogene accounts for the amplification in cancer, such as MET gene amplification." (PMID 24113161, 2013). "Targeting of MET signaling by MET-TKIs is therefore a potentially valuable therapeutic approach for patients with MET amplification–positive gastric cancer." (PMID 23327903, 2013). "We thus performed PCR-based screening for MET copy number in 266 surgically resected specimens of gastric cancer and then applied FISH analysis to the 15 cases showing the highest gene copy numbers." (PMID 23327903, 2013). "Couple of current studies addressed the candidates of new molecular targets for gastric cancer, including MET amplification and a epigenetically regulated tumor-suppressor, galecin-7." (PMID 24113161, 2013). "Previous studies based on FISH analysis have detected MET amplification in up to 4% of patients with gastric cancer." (PMID 23327903, 2013). "The PCR-based assay thus revealed a high copy number for MET only in gastric cancer cell lines previously shown to be positive for MET amplification by FISH." (PMID 23327903, 2013).
gastric cancer (continued). "In gastric cancer cells with MET amplification, the MET-TKIs markedly inhibited AKT, ERK, and STAT3 signaling and triggered apoptosis, whereas such effects were not evident in cells without MET amplification." (PMID 23327903, 2013). "Numerous studies have reported that c-MET is overexpressed in a variety of carcinomas including lung, breast, ovary, kidney, colorectal, thyroid, liver, and gastric carcinomas." (PMID 24205104, 2013). "We rendered a MET amplified gastric cancer cell line, GTL16, resistant to c-Met inhibition with prolonged exposure to a c-Met inhibitor, PF-04217903 (METi)." (PMID 22745804, 2012). "The chromosomal rearrangement TPR-MET, observed in gastric cancers, results in the expression of a completely intracellular fusion protein that comprises a constitutive dimerization motif and the MET intracellular domain." (PMID 22973229, 2012). "This study shows SRC, c-MET, and CRK genetic variants can be susceptible genetic factors for the development of gastric cancer by controlling signals through the CagA transduction pathways." (PMID 22383989, 2012). "The aim of this study was to evaluate the frequency of c-MET overexpression and its relationship with clinicopathological variables in gastric cancer of Iranian population using tissue microarray." (PMID 22640970, 2012). "Our findings suggest that SRC, c-MET and CRK play a key role in gastric carcinogenesis by modulating CagA signal transductions and interaction between CRK gene and phytoestrogens modify gastric cancer risk." (PMID 22383989, 2012). "c-MET high expression was also significantly higher in stage 3 and 4 (80%) compared to stage 1 and 2 (44%) of gastric cancer (P = 0.044)." (PMID 22640970, 2012). "To anticipate potential resistance, we utilized an in vitro screen to select for METi resistant clones of GTL16, a c-Met dependent gastric carcinoma cell line that harbors a high-level focal amplification of the MET gene locus." (PMID 22745804, 2012). "Overexpression and amplification of c-MET have been demonstrated in many tumors, including colorectal, thyroid, renal cell, ovary, breast, pancreas, prostate, liver, and melanoma and in gastric carcinoma." (PMID 22640970, 2012). "Amplification of MET is often responsible for the activation of MET signalling, with such amplification occurring most frequently (10–20%) in gastric cancer." (PMID 21730976, 2011). "Amplification of the proto-oncogene MET is a frequent (10–20%) molecular abnormality in gastric cancer, and a MET-tyrosine kinase inhibitor (TKI) has been shown to induce apoptosis in gastric cancer cells with MET amplification." (PMID 21730976, 2011). "We and others previously showed that the MET-TKI induced a substantial increase in the frequency of apoptosis in MET-activated gastric cancer cells." (PMID 21730976, 2011). "Our findings predict that gastric cancer tumors bearing constitutive activation of HER family members are poorly responsive to MET inhibition, even if this receptor is constitutively active." (PMID 20500904, 2010). "In our work we show that in gastric cancer cell lines "addicted" to MET, activation of HER family members, through ligand stimulation or mutational activation, contributes to overcome MET inhibition." (PMID 20500904, 2010). "The receptor tyrosine kinase MET is constitutively activated in many gastric cancers and its expression is strictly required for survival of some gastric cancer cells." (PMID 20500904, 2010). "GTL16 gastric cancer cells are the prototype of "MET addicted cells", containing 11 copies of the MET locus, located on a marker chromosome." (PMID 20500904, 2010). "Molecular analyses performed in gastric cancer samples have shown that among the genes frequently altered in this tumor are tyrosine kinase receptors of the MET and HER families." (PMID 20500904, 2010).
gastric cancer (continued). "We and others have shown that gastric cancer cells bearing amplification of the MET gene and overexpression of the receptor, are "addicted" to this oncogene, since its inhibition results in impairment of tumor growth." (PMID 20500904, 2010). "Altogether these findings suggest that the activation of the HER family receptors confers resistance to PHA-665752 in gastric cancer cells displaying MET overexpression due to gene amplification." (PMID 20500904, 2010). "The MET gene has been shown to be amplified in human gastric cancers and gastric cancer cell lines; amplification is known to be responsible for receptor overexpression and ligand-independent constitutive activation." (PMID 20500904, 2010). "MET amplification in gastric cancer cell lines has recently been correlated with high sensitivity towards MET inhibitor." (PMID 19238632, 2008). "For gastric cancer, the predominant mechanisms that confer resistance to HER2-targeted therapy have been identified as the loss of HER2 amplification after treatment and the activation of alternative pathways, such as MET and EGFR." (PMID 41614808, 2025). "In gastric cancer, it was suggested that the MET amplification is often accompanied by human epidermal growth factor receptor 2 (HER2) overexpression, and co-expression of MET and HER2 can synergistically enhance tumor invasion, and metastasis, which is a crucial factor for poor prognosis." (PMID 39991569, 2025). "This case underscores the potential and limitations of MET inhibitors in gastric cancer." (PMID 40860829, 2025). "Additionally, AFP acts as a co-chaperone of heat shock protein 90 (HSP90), stabilizing oncoproteins c-MYC and c-MET, thereby facilitating tumor progression in liver and gastric cancers." (PMID 40485723, 2025). "In NSCLC, early trials combining MET inhibitors with immune checkpoint blockade have yielded promising results, and similar strategies could be evaluated in gastric cancer." (PMID 40860829, 2025). "Recently, the significant therapeutic effect of SRI31215, a novel small molecule inhibitor of pro-HGF activation (inhibitor of hepsin, matriptase and HGF activator: similar function with HAIs), has been reported in MET-amplified non-small cell lung and gastric cancer cells." (PMID 40299447, 2025). "Overexpression of MET was observed in liver metastases of colorectal cancer and gastric cancer." (PMID 40076928, 2025). "Moreover, in gastric cancer, HGF and c-MET have been implicated in the accumulation of Tregs in peripheral blood." (PMID 40281554, 2025). "In addition to melanoma, PLEKHA5 has also been associated with gastric cancer, with studies finding that tyrosine phosphorylation of PLEKHA5 is MET-dependent and associated with MET expression and phosphorylation." (PMID 38818040, 2024). "Similarly, in gastric cancer, MET mRNA expression through RNA ISH aligns well with c-Met protein expression by IHC." (PMID 39123483, 2024). "Picomolar activity against cancer cell lines from various solid tumors, including lung, colorectal, and gastric cancers, was exhibited by this nonagonistic c-MET antibody linked to the pyrrolobenzodiazepine (PBD) toxin-linker tesirine." (PMID 39664377, 2024). "Furthermore, in gastric cancer, HGF and c-MET were implicated in Treg accumulation in peripheral blood." (PMID 39664377, 2024). "Interestingly, a MET-positive gastric carcinoma cell line became resistant to MET inhibitors through bypass activation of the EGFR pathway." (PMID 39769452, 2024). "In the preliminary investigation using RNAseq data of gastric cancer patients’ tissue, we found that the combined evaluation of RTKs, such as MET and FGFR2 amplification, could identify the specificity of gastric tumor cells when compared to normal tissue." (PMID 38137393, 2023). "Another in vitro study suggests that MET inhibitor–induced autophagy may mediate resistance to MET inhibitors, including tepotinib, specifically in gastric cancer models." (PMID 36999986, 2023).
gastric cancer (continued). "In this review, we analyzed all studies performed on gastric cancer with MET-inhibitors." (PMID 37046637, 2023). "Other studies in gastric cancer cell lines showed that anti-HGF inhibited further cell growth and that HGF could be produced by gastric fibroblasts, the invasiveness of which could be promoted by MET expression on gastric cancer cells." (PMID 37046637, 2023). "Additionally, RNA silencing of c-MET using lentivirus in gastric cancer cells, leads to suppression of peritoneal dissemination showing a proliferative and metastatic role of c-MET." (PMID 35069735, 2022). "Similarly, we recapitulated the known associations between amplifications of a chromosomal segment 7q31 including the MET oncogene, and sensitivity of esophageal/gastric cancer to crizotinib and also 3 other MET inhibitors (FDRs < 6%)." (PMID 35614096, 2022). "There were few reports of Crizotinib in gastric cancer patients with c-MET amplification." (PMID 35568828, 2022). "Among them, we found that MET was highly expressed in single cells of tumor samples and cancerous mucous cells, and it has been reported in the literature that it is a proto-oncogene, but there are few reports in gastric cancer." (PMID 35659682, 2022). "However, there are still problems that are worthy of future research, such as how Cy induces apoptosis in gastric cancer cells and the specific mode of action of Cy on MET downregulation." (PMID 34830011, 2021). "IFNγ may additionally enhance gastric cancer immunosuppression by inducing hepatocyte growth factor receptor (HGFR/MET)-mediated PD-L1 expression." (PMID 33406733, 2021). "In several different cancers, TPR is present through fusion genes, which is formed by coiled-coil motif in TPR with some kinase partner genes such as MET (gastric cancer), NTRK1 (thyroid carcinoma), FGFR1 (myeloproliferative syndromes), and ALK (lung adenocarcinoma)." (PMID 34722501, 2021). "Herein, we reported a patient diagnosed with gastric cancer metastasized to multiple bones, along with lymphangitis carcinomatosa in lungs, harboring Her-2 and c-MET amplification with poor PS, positively responded to combinational therapy with trastuzumab and crizotinib." (PMID 34516491, 2021). "In addition, HPA indicated low levels of DEPDC1 protein in normal stomach tissues and moderate expression level in gastric cancer tissues; however, the expression levels of MET are the opposite." (PMID 34386426, 2021). "In gastric cancer, specifically sfRON was found to confer resistance to therapeutic MET targeting." (PMID 32272784, 2020). "The cBioportal Web tool was utilized to explore HGF and c-MET gene alterations in gastric cancer." (PMID 32788873, 2020). "In fact, stimulation of MET-amplified gastric cancer cells with the HER agonist heregulin (HRG) could ameliorate the cytotoxic effects of MET inhibitors." (PMID 33374770, 2020). "MET gene amplification has been reported to exhibit constitutive ligand‐independent MET activation through receptor dimerization, which acts as a primary “oncogenic driver” that might indicate poor prognosis in patients with gastric cancer." (PMID 34766112, 2020). "Inappropriate activation of MET signaling occurs in a several cancer types, including gastric cancer and promotes tumor cell growth, survival, migration and invasion, namely the Invasive growth genetic program which is involved tumor spreading and metastatic growth." (PMID 32751137, 2020). "MET activation is an established resistance factor for cetuximab treatment in gastric cancer." (PMID 32119655, 2020). "PIM kinases have also been identified as mediators of drug resistance in other contexts, including resistance to MET inhibitors in lung or gastric cancers, suggesting the application of PIM inhibition to other therapeutic combinations in additional tumor indications." (PMID 32391118, 2020). "Additionally, HGF promotes the formation of anchorage-independent colonies of MET-amplified gastric cancer cells." (PMID 32435640, 2020).
gastric cancer (continued). "Therefore, large-scale clinical trials should be conducted using patients that experienced c-Met targeting therapy to study volumetric PET/CT parameters to predict prognosis in patients with gastric cancer patients in relation to c-MET expression." (PMID 31395059, 2019). "Indeed, phase III trials of onartuzumab and rilotumumab treatment of patients with gastric cancer overexpressing c-MET and a considerable number of phase I and phase II trials of agents targeting c-MET are ongoing." (PMID 31395059, 2019). "MET inhibitors were also tested in gastric cancer cell lines." (PMID 31557260, 2019). "Overexpression of c-MET has been proven to indicate poor prognosis in patients with gastric cancer." (PMID 31395059, 2019). "This suggested that the volumetric parameters on PET/CT might serve as a tool to stratify patients with gastric cancer for potential c-MET targeting therapy." (PMID 31395059, 2019). "In view of the pivotal roles of MET in cell growth, proliferation and survival, deregulation of MET signaling has been identified in different types of cancers including thyroid, lung, breast, gastric carcinoma, liver, colon, kidney, and ovary." (PMID 31369639, 2019). "miR-206, miR-34a and miR-1 could suppress gastric cancer by mediating c-MET, the miRNAs-MET pathway could serve as a promising treatment modality in gastric cancer." (PMID 30360560, 2018). "We previously reported that M-COPA (2-methylcoprophilinamide), a Golgi disruptor, suppressed the growth of gastric cancers overexpressing receptor tyrosine kinases (RTKs) such as hepatocyte growth factor receptor (MET) via downregulating their cell surface expression." (PMID 29416720, 2018). "miR-206 levels were decreased in gastric cancer specimens, however, c-MET was overexpressed." (PMID 30360560, 2018). "Importantly, they confirmed overexpression of HGF and c-MET are correlated with peritoneal dissemination and poor prognosis in gastric cancer." (PMID 30360560, 2018). "miR-34a has been described as a tumor-suppressor gene in HCC and gastric cancer by targeting c-MET." (PMID 30360560, 2018). "A functional connection between the MET and FGFR1 pathways is supported by the finding that FGFR inhibitions sensitized MET-amplified gastric cancer cells to treatment with an anti-MET antibody and by the reactivation of MET that drove MAPK activity as a consequence of AR to the FGFR1 inhibitor." (PMID 30140389, 2018). "It has been mentioned that SU11274 may suppress tumor cell growth in HCC and gastric cancer via specifically inhibiting c-MET phosphorylation, and the antitumor function also been observed in CRC." (PMID 30360560, 2018). "In addition, an increased level of miR-34a was shown to inhibit the metastatic potential via the suppression of MET signaling pathway in gastric cancer cells." (PMID 30005681, 2018). "Several c-MET inhibitors have been developed as anticancer drugs in gastric cancer treatment." (PMID 30360560, 2018). "Rhodocetin-αβ-induced breakdown of the tumor vessel wall barrier may be relevant also for other NRP1- and MET-expressing malignancies in which VM occurs, for example glioma/astrocytoma, prostate cancer, and gastric cancer." (PMID 29854288, 2018). "To clarify whether an additional MET amplification can provide resistance to afatinib treatment in gastric cancer cell lines, we performed experiments with the Hs746T cell line." (PMID 29325228, 2018). "Future strategies for c-Met kinase receptor inhibitors evaluation in gastric cancer will require stringent and standardized methods to assess MET amplification, will likely use a high threshold for the definition of amplification, and will consider amplification clonality in patient selection." (PMID 29108334, 2017). "MET amplification is a clinically validated therapeutic target in gastric cancer." (PMID 28881678, 2017).